RNU6-230P (RNA, U6 small nuclear 230, pseudogene)
Gene: Small nuclear RNA gene on chromosome 3 (125,119,097 to 125,119,200, reverse strand). Ensembl gene ENSG00000199327.
Homologues: Orthologues: chimpanzee U6 (98% identical), guinea pig U6 (90% identical), rat U6 (85% identical), mouse Gm23940 (79% identical), pig U6 (78% identical), pig U6 (75% identical). Paralogues in human: RNU6-946P (90% identical), RNU6-1011P (89% identical), RNU6-1029P (89% identical), RNU6-12P (89% identical), RNU6-13P (89% identical), RNU6-166P (89% identical), RNU6-25P (89% identical), RNU6-31P (89% identical), RNU6-32P (89% identical), RNU6-33P (89% identical), RNU6-41P (89% identical), RNU6-492P (89% identical), and 1288 more.